CTLA4 (cytotoxic T-lymphocyte associated protein 4)
Diseases named in the same sentence as CTLA4 in open-access papers (continued):
Sharing a sentence is not in itself a finding about the gene and the disease.
tumor (continued). "In line with this, an on-treatment increase in intratumoral Teff:Treg ratio conditions optimal immune control of the tumor under anti-CTLA-4 in a number of models." (PMID 33602280, 2021). "Checkpoint inhibitors can effectively block the inhibitory immunoregulation of PD-1/PD-L1, CTLA-4 and other immune checkpoints, so as to indirectly strengthen the anti-tumor immune response and improve the effect of immunotherapy." (PMID 34194437, 2021). "For example, tumor-infiltrating Tregs (C08_CD4.CTLA4, C10_CD4.CXCL13) and exhausted T cells (C04_CD8.LAYN) clustered together, demonstrating a huge difference between these cells and others." (PMID 33674641, 2021). "CTLA-4 and PD-1 are the most well-studied examples of T cell immune checkpoint molecules and tumor cells exploit these molecules to evade host immunity." (PMID 33634137, 2021). "Of note, the combination of a CD40 agonistic monoclonal antibody with PD-1 or CTLA-4 inhibition synergistically induced an anti-tumour immune response resulting in tumour regression in another mouse model of PDAC." (PMID 34439389, 2021). "Anti-CTLA-4 and anti-PD-L1 monoclonal antibodies effectively block these pathways resulting in the re-activation and clonal expansion of tumour-reactive lymphocytes." (PMID 35047074, 2021). "In pre-clinical studies, blockade of CTLA-4 led to rejection of lymphoma, colorectal, renal and fibrosarcoma cancer cell lines in mice and activation of human tumour-specific CTLs." (PMID 33401460, 2021). "In preclinical models of breast and colon cancer, anti-PD-1 and anti-CTLA-4 therapy resulted in tumour regression, increased perfusion and reduced tumour hypoxia." (PMID 33499003, 2021). "The immune-related pseudogenes signature can assess survival and immune checkpoint inhibitor response of patients with anti-PD-1 and anti-CTLA4 therapy, potentially enabling more personalized and precise tumor immunotherapy in the future." (PMID 34193185, 2021). "For instance, ligands of CTLA4 and PD-1 highly expressed in colorectal cancer suppress T cell activity and maintain tumor Tregs." (PMID 33406733, 2021). "Flow cytometric analysis of Ki67 (D) and CTLA-4 (E) expressions of Treg cells in the tumor in Cd300afl/fl (n = 9 in D, n = 3 in E) and Cd300afl/fl;ItgaxCre mice (n = 10 in D, n = 4 in E)." (PMID 34751648, 2021). "For the combination of photothermal therapy and anti-CTLA-4, 55% of the mice treated survived at 100 days after tumor inoculation and are likely cured." (PMID 33411055, 2021). "Combining PV-induced immunogenic oncolysis with CTLA-4 and/or PD-1 blockade allows achieving a double goal, i.e., tumor cell killing and activation of the immune system against the tumor." (PMID 33477757, 2021). "The results showed that this treatment regimen dramatically reduced the tumor metastasis in mouse lungs compared with anti-PD-1 + anti-CTLA-4 Abs and PBS treatment." (PMID 34907171, 2021). "Currently, therapies targeting the classical immune checkpoint pathways responsible for inducing the exhausted T cell phenotype, PD-1 to PD-L1 and CD80/CD86 to CTLA4, are being used to reverse the dysfunctional state and enhance anti-tumor immune response." (PMID 33790740, 2021). "Weber predicted 10 years ago that abrogation of the CTLA-4 function results in immune stimulation, tolerance breakdown and eventually tumor eradication." (PMID 33151369, 2021). "Programmed cell death protein 1 (PD-1) and cytotoxic T lymphocyte-associated antigen 4 (CTLA-4) are co-inhibitory ICPs; they are expressed on activated tumor-specific CD4+ cells and CD8+ T-lymphocytes, and inhibit the progression of the immune reaction." (PMID 33783613, 2021). "We previously demonstrated that the combinatorial use of a cancer vaccine, anti-PD-1 and anti-CTLA-4 led to improved overall survival in ID8 tumor-bearing mice." (PMID 34572778, 2021).
tumor (continued). "The results showed that PL1-OX40 (ψ) + anti-OX40 Ab enhanced antitumor effects of anti-PD-1 + anti-CTLA-4 Abs immunotherapy, inhibited tumor growth, and extended mouse survival." (PMID 34907171, 2021). "Thanks to its role in inhibiting the immune response against the tumor, CTLA-4 correlates with a poor prognosis in BC patients." (PMID 33777750, 2021). "Compared with ICI monotherapy, the combination of HIF-1-mediated ectoenzyme ENTPD2 inhibitors and ICI (anti-CTLA-4/PD-1) significantly enhanced T cell infiltration into the tumor and extends the survival of tumor-bearing mice." (PMID 33422072, 2021). "Immune checkpoint inhibitors (ICI) are a class of monoclonal antibodies that modulate tumor tolerance among immune cells by blocking specific inhibitory receptor-ligand interactions to overcome immune exhaustion (e.g. anti-CTLA-4, anti-PD-1)." (PMID 33937052, 2021). "Encouragingly, anti-CTLA4 treatment significantly decreased tumor growth in IRF8-transgenic mice compared to wild-type mice." (PMID 35011582, 2021). "Anti-CTLA-4 monoclonal antibodies have also been shown to induce the release of TNFα against tumour cells via CD16 binding to antibody-bound tumour cells, and simultaneously to induce Treg inactivation." (PMID 33995362, 2021). "ICs, such as CTLA-4, PD-1 and PD-L1, can be overexpressed on immunosuppressive tumor-specific regulatory T (Treg) cells." (PMID 33467713, 2021). "The blockade of CTLA4 attenuates its immunosuppressive effect, leading to sensitisation to tumour antigens." (PMID 33802937, 2021). "A study found that IgG2a isotype anti-CTLA-4 antibodies had the most effective anti-tumor effects compared with other isotype antibodies in mouse tumor models." (PMID 34743730, 2021). "Combination of CTLA4 with RT in a dual murine model of mesothelioma enhanced the tumor regression, relative to either single treatment." (PMID 34068491, 2021). "Reck also believes that because anti-CTLA-4 only plays a role in the immune activation stage, and lacks subsequent immune effectors, it cannot effectively stimulate sufficient anti-tumor immune responses." (PMID 33531977, 2021). "Mechanistically, at an early time point, secondary tumor from mice treated with anti-CTLA-4 Ab and PLGA-R837@Cat had a higher number of CD8+ T cells when compared with those treated with single agents or other combinations." (PMID 33800368, 2021). "On the other hand, anti-CTLA-4 treatment induced significant tumor growth inhibition and significantly promoted survival in both models." (PMID 34774008, 2021). "We propose that the AMPK activator can display synergic antitumor effect in murine tumor models, supporting their potential clinical use when combined with anti-PD-1 antibody, anti-CTLA-4 antibody, or a HMGCR inhibitor." (PMID 34649584, 2021). "ICIs such as anti-CTLA-4, anti-PD-1, and anti-PD-Ligand 1 (PD-L1) antibodies have been developed to restore the immune system’s ability to mount an anti-tumor immune response." (PMID 34898551, 2021). "Based on GSE110224 and GSE25070 datasets, we have found that CTLA-4 expression is substantially upregulated in CRC tissues compared to adjacent non-tumor samples." (PMID 34067631, 2021). "In clinical practice, anti-PD-1/PD-L1 and anti-CTLA-4 therapy proved effective for restoring the anti-tumor T-cell-mediated immune responses." (PMID 34675914, 2021). "Given the different activated states of PD-L1 and CTLA-4 pathways in tumor tissues, we further investigated the synthesized effect of TumorPD-L1 and TILsCTLA-4 expression on prognosis in patients with ICC." (PMID 34526987, 2021). "This led to an increase in tumor rejection compared to bacterial therapy alone or the combination of anti PD-L1 and anti-CTLA-4." (PMID 34203478, 2021). "Tumor-specific Tregs residing at the TME express high levels of CTLA-4 and OX40, and in situ injection of anti-CTLA-4 and anti-OX40 together with CpG can deplete tumor-infiltrating Tregs." (PMID 35111169, 2021).
tumor (continued). "The activation of AMPK combined with anti-PD-1 and anti-CTLA4 antibodies or with a HMGCR inhibitor exhibited synergic anti-cancer activity in murine tumor models, supporting their potential clinical use." (PMID 34649584, 2021). "Unlike the TC-1-induced tumor growth, which was negligibly reduced by anti-CTLA-4, TC-1/dCD80-1-induced tumor growth was markedly inhibited by the antibody." (PMID 33923750, 2021). "The combination of anti-PD1, anti-CTLA4 and adoptive transfer of autologous TILs led to tumor regression, encouraging the path of combination immunotherapies in ovarian cancer." (PMID 34869042, 2021). "CTLA4 is an important immune checkpoint for tumor immunotherapy, such as the CTLA4 inhibitor ipilimumab, which has been tested in clinical trials in multiple types of tumors." (PMID 33575321, 2021). "CTLA-4 blockade was observed to indirectly influence NK cells by reducing Treg and tumor-related immune suppression, but the potential ADCC effect by NK cells and its possible role in anti-CTLA-efficacy is still unclear." (PMID 33572396, 2021). "The expression levels of CXCR3 and CTLA4 were higher in tumor tissues than those in normal tissues (P < 0.05)." (PMID 34218795, 2021). "The addition of anti-CTLA-4 to CpG+OX40 has been shown to improve the abscopal response in a two-tumor A20 model by increasing the number of IFN-gamma producing CD4+ and CD8+ T cells and further decreasing the Treg frequency in the TME." (PMID 34868010, 2021). "After 28 days, the mice receiving the IL‐2 and anti‐CTLA4 Ab‐loaded aAPCs demonstrated significantly smaller tumor size as well as increased survival, compared to the groups being treated with IL‐2 or anti‐CTLA4 Ab‐loaded aAPCs." (PMID 33898169, 2021). "Immunochemistry of tumor tissues of patients suggest that the expression levels of PD-1, PD-L1, CTLA-4, TIM-3, and LAG-3 are significantly higher in BRAF mutated samples than in BRAF wild-type samples." (PMID 34381786, 2021). "Increased expression of genes associated with tumor cell immune susceptibility, immune cell recruitment, and cytotoxic T lymphocyte activation were observed in tumors of mice treated with BEMPEG, anti-CTLA-4, and RT." (PMID 33937052, 2021). "Expression of PD-1 has also shown significant correlations with CTLA-4 (p < 0.001) and TIM-3 on TILs (p = 0.001), whereas CTLA-4 expression on TILs correlated with CTLA-4 expression on the tumor (p < 0.001) and TIM-3 expression on TILs (p = 0.018)." (PMID 33823818, 2021). "In the tumor microenvironment, the expression of CTLA-4 in tumor infiltrating regulatory T cells (Treg) is increased, thereby inhibiting the activation of tumor antigen-specific T cells, proliferation and anti-tumor function, realize tumor escape." (PMID 35069586, 2021). "In contrast, tumor Treg had non CTLA-4 collaboration genes upregulated ranging from 10 genes to 50 genes, which were higher than that of normal tissue Treg and non-tumor diseased tissue Treg." (PMID 34084175, 2021). "The HCT-116 xenografted mice treated with CTLA-4 KO CTLs demonstrated repressed tumor growth and prolonged survival relative to those in the control group." (PMID 33466394, 2021). "Tumor tissue restricts T cell function and induces T cell apoptosis through overexpression of immune checkpoint (PD-L1, CTLA-4)." (PMID 34930293, 2021). "Enhanced T cell responses against known tumor antigens observed in the periphery of anti-CTLA-4 treated patients suggests this systemic response to be at least in part tumor specific." (PMID 33602280, 2021). "For instance, release of soluble HLA-G by tumor cells up-regulates CTLA-4, PD-1, TIM-3, and CD95 on CD8 T cells impacting their anti-tumor activity." (PMID 34447383, 2021). "This is not surprising, as this model does not respond well to other immune checkpoint therapies, including PD-1/CTLA-4 blockade either, unless combined with vaccines or chemotherapies that enhance tumor immunogenicity." (PMID 33547304, 2021).
tumor (continued). "In human patients, Akkermansia levels positively correlated with partial response or stable disease, and in mouse models, repletion of Akkermansia via oral gavage was able to repotentiate tumor response to CTLA-4 and PD-L1 therapy." (PMID 34256732, 2021). "For example, tumor-infiltrating T cells express high levels of the coinhibitory molecules PD-1 and CTLA-4, thereby enabling immune checkpoint blockade therapies to prevent the ligand-binding–induced inhibitory signals." (PMID 34290401, 2021). "Both CTLA-4 and PD-1/PD-L1 pathways play a significant role in tumor evasion through down regulation of the immune response." (PMID 34268109, 2021). "Our results suggest that Rab37/IL-6/PD-1 functions in the same axis and thus provide a rationale design using combined treatment of α-IL-6 and α-CTLA-4 to promote anti-tumor efficiency." (PMID 34093869, 2021). "Local expression of anti-CTLA4 antibodies resulted in 43-fold higher concentrations in tumor than plasma." (PMID 34367111, 2021). "The combination treatment resulted in significantly reduced tumor growth compared with AZD1152 (p < 0.001) or anti-CTLA4 (p = 0.019) alone and significantly improved survival (p = 0.002)." (PMID 33123754, 2021). "Combining HBI-8000 with CTLA-4 Ab produced a highly significant delay in tumor progression, with 20% of tumor-bearing mice experiencing complete regression." (PMID 34461854, 2021). "The exhaustion of CTLs is a mechanism that occurs in the TME, suppressing the immune response of CTLs against tumor cells through the expression of inhibitory receptors such as PD-1, CTLA-4, and LAG-3." (PMID 34572263, 2021). "One of the well-known actions of the anti-CTLA-4 antibody is to downregulate Tregs in the tumor microenvironment." (PMID 34956912, 2021). "A possible mechanism involved in tumor evasion is the upregulation of immune checkpoints, such as PD-1, PD-L1 or CTLA-4." (PMID 34321536, 2021). "As with other studies, combinaton with single-agent ICPI enhanced therapy, however triple therapy (OV/PD-1/CTLA-4) led to complete, durable tumour regression." (PMID 34733287, 2021). "Even greater anti-tumor responses were seen when radiation, immunocytokine, and anti-CTLA-4 blockade were combined in immunocytokine antigen-positive tumors." (PMID 33803078, 2021). "In clinical tumor immunotherapy, the main immune checkpoint inhibitors currently in use include CTLA-4 inhibitors and PD-1 inhibitors." (PMID 34777359, 2021). "According to this distribution, PEGylated anti-CTLA-4 administration significantly delayed tumor growth when compared with other treatments." (PMID 33800368, 2021). "The success of this combinatorial setting was proposed to be caused by a GVAX-induced expansion of mesothelin-specific CD8+ T cells within the tumor microenvironment, thereby enhancing the efficacy of the anti-CTLA-4 antibody treatment." (PMID 33710604, 2021). "Expression of anti-CTLA-4 (mRP2) further improved anti-tumor activity in the mouse A20 model, and combining mRP1 with anti-PD-1 antibody significantly improved the inhibition of non-injected tumors." (PMID 34578321, 2021). "Sunitinib alone substantially extended overall survival (median survival: 15 vs 24 d; p < 0.05) of B16F10 tumor‐bearing mice, and combined with anti‐CTLA‐4 enhanced survival benefit (median survival time: 15 vs 57 d; p < 0.05)." (PMID 33510997, 2021). "CRISPR-mediated knock out of CTLA-4 has indeed been found to enhance the anti-tumor activity of CTLs." (PMID 34681881, 2021). "It is important to note that certain species of Bacteroidetes, such as B. thetaiotomicron, and B. fragilis have been paradoxically shown to improve tumor control with CTLA-4 therapy." (PMID 34256732, 2021). "Based on the in vitro data and biodistribution studies, the NF9006 tumor mouse model appeared useful to investigate the potential of [177Lu]Lu-DOTA-folate to enhance anti-CTLA-4 immunotherapy." (PMID 33078260, 2021).
tumor (continued). "We also detected higher levels of infiltrating CD8 T lymphocytes with higher granzyme B expression in the YUMM1.7-CM generated tumors and most importantly, suppression of tumor growth in response to anti-CTLA-4/anti-PD-1 checkpoint blockade regimen." (PMID 34295826, 2021). "Inversely, in pathological (neoplastic) conditions, CTLA-4 activation inhibits in the activation, proliferation, and production of tumor antigen-activated T-cells in the tumor microenvironment." (PMID 34361985, 2021). "Tumor-infiltrating CD4+ T cells upregulated PD-1, cytotoxic T-lymphocyte-associated protein-4 (CTLA-4), T cell immunoglobulin and mucin domain-3 (TIM-3) and LAG-3." (PMID 34660608, 2021). "Downregulation of HLA class I and upregulation of immune checkpoint proteins (PD-1, CTLA-4, and PD-L1) are known to help the tumor to escape the control of the immune system." (PMID 35003017, 2021). "Immune checkpoint molecules such as PD-1, PD-L1 and CTLA4 also play a pivotal role in immunosuppression of the tumor microenvironment." (PMID 33688997, 2021). "Tregs, which are abundant in the tumor stroma is a specific subgroup of CD4+ T cells expressing the transcription factor Foxp3, CD25 and cytotoxic T-lymphocyte-associated antigen-4 (CTLA-4)." (PMID 34062992, 2021). "Since CTLA-4 can regulate the activity of T-cells and APCs, e.g., DCs, this immune checkpoint can induce immune tolerance, facilitating tumor evasion." (PMID 33692796, 2021). "Antibody-mediated targeting of MARCO on TAMs was shown to repolarize macrophages; reduce tumor growth and metastasis; and enhance the effect of CTLA-4 ICB in murine models of mammary cancer, melanoma, and colon carcinoma." (PMID 33924237, 2021). "As expected, CTLA-4 expression was also positively correlated with the estimated proportions of regulatory T cells (Tregs) in each tumor type." (PMID 34376232, 2021). "The literature has indicated that immunotherapy targeting PD-1 and CTLA-4 specifically increases CXCL9 and CXCL10 from tumor-associated macrophages in tumor tissues, whereas CXCL9 and CXCL10 are induced by IFNγ in the tumor microenvironment." (PMID 34680466, 2021). "The therapeutic effect became even more evident when the anti-CTLA-4 agent was administered between cycles of chemotherapy (cisplatin) and especially at the initial stage of tumor growth." (PMID 34199722, 2021). "Immune checkpoints were one of the reasons for tumor immune escape, we examined the relationship between immune-related genes and major immune checkpoints (PD-1, PD-L1, CTLA4, LAG3, and VSTM3)." (PMID 35252217, 2021). "In a murine TRAMP-C2 prostate cancer cell line model, the combination of anti-CTLA-4 with cryo led to improved antitumor immune responses and tumor rejection." (PMID 34737281, 2021). "The mechanisms underlying aberrant PD‐L1 expression have been intensively studied, but the mechanism underlying high level of immune checkpoint protein, such as PD‐1 and CTLA4, in tumour‐infiltrated T cells remain largely unexplored." (PMID 33325636, 2021). "In 2013, a phase I clinical trial in which ipilimumab (anti-CTLA-4 mAb) was combined with nivolumab (anti-PD1 mAb) reported tumor regression in 50% of treated patients." (PMID 34572847, 2021). "LAG-3 is, along with PD-1/PD-L1 and CTLA-4, a promising target in cancer immunotherapy, since it plays a pivotal role in anti-tumor immunity." (PMID 33925565, 2021). "Control rates vary for other therapies, from 64% for combined immunotherapy (CTLA-4 plus anti-PD-1) to 43% for tumor-infiltrating lymphocyte therapy." (PMID 34513843, 2021). "This is a distinct mechanism of CTLA-4 blockade-induced immune response compared to anti-PD-1, where the expansion of tumor-infiltrating exhausted CD8 T cells is believed to be the main mechanism of action." (PMID 34046035, 2021). "The treatment of immune checkpoint inhibitors represented by CTLA-4/PD-1 inhibitors is undoubtedly a major progress in anti-tumor therapy." (PMID 34616403, 2021).